BRCA1 (BRCA1 DNA repair associated)
Diseases named in the same sentence as BRCA1 in open-access papers (continued):
Sharing a sentence is not in itself a finding about the gene and the disease.
ovarian carcinoma (continued). "Ovarian cancer patients with tumours harbouring loss-of-function mutations in HRR genes other than BRCA1/2 may constitute a small, molecularly identifiable and clinically relevant population who derive treatment benefit from olaparib similar to patients with BRCAm." (PMID 30353044, 2018). "Additionally, the woman – BRCA1 carrier who chooses to undergo bilateral salpingoophorectomy more closely to the age of 40, may face an increased risk of ovarian cancer which is estimated to be 4%." (PMID 30340058, 2018). "28.3% of recurrent ovarian cancer tumors contain secondary mutations as compared with only 3.1% in primary tumors, while 46.2% of platinum resistant tumors have secondary mutations that restored the function of BRCA1/2 as compared with 5.3% that are sensitive to platinum drugs." (PMID 29459887, 2018). "Some clinicians may perceive that having their ovaries surgically removed is not an option for some patients, given that guidelines recommend oophorectomy to be considered for all women who are around the age of 40 and at an increased risk of ovarian cancer due to a confirmed BRCA1/2 gene mutation." (PMID 30428865, 2018). "Interestingly, the ARIEL2 study included patients with germline BRCA1/2-wild type platinum sensitive recurrent ovarian cancers, but utilized a next generation sequencing loss of heterozygosity (LOH) assay that as a biomarker for HR deficiency in BRCA1/2-wild type platinum sensitive ovarian cancers." (PMID 28829366, 2017). "Furthermore, the CGH-array analysis performed in an ovarian carcinoma showed high genomic instability, which further reinforces the hypothesis of a DNA repair defect such as BRCA1 deficiency." (PMID 28186987, 2017). "The mutational spectrum of BRCA1/2 in Moroccan population is becoming partially characterized, thanks to few local genetic centers, including our own, which developed oncogenetics consultation for familial forms of breast and ovarian cancers and molecular analysis of BRCA genes." (PMID 28577564, 2017). "The rate of somatic BRCA1/2 mutations in other cancers may differ from those for ovarian cancer." (PMID 28525389, 2017). "This has led us to investigate the baseline clinical characteristics of patients with advanced BRCA1/2 mutation ovarian cancer, including the effects of platinum sensitivity as potential factors that may be used in the prediction of patients benefit to olaparib." (PMID 28454085, 2017). "Our results clearly demonstrate that the detection of both germline and somatic BRCA1/2 mutations in ctDNA from ovarian cancer patients is feasible and may be a valuable complementary tool for identification of somatic alterations when the standard diagnostic procedures are insufficient." (PMID 29254167, 2017). "Notably, reduced BRCA1 protein expression in both inherited and sporadic forms of breast and ovarian cancer has been associated with a significant reduction in the levels of BRCA1 mRNA, thereby supporting the utility of BRCA1 transcript levels as a surrogate marker of BRCA1 function." (PMID 27534398, 2016). "In addition, a study examining the role of taxane monotherapy in germline BRCA1/2 mutation carriers with relapsed ovarian cancer found a significant survival benefit in patients with initially platinum-sensitive disease compared to those with platinum-resistant disease." (PMID 27191893, 2016). "BRCA1 and BRCA2 germline mutations are known risk factors for ovarian cancer, and it has been reported that up to 44% of patients without a family history of ovarian cancer harbour a germline BRCA1 or BRCA2 mutation, and as such may act as first alert for descendants." (PMID 26745875, 2016). "To test whether the expansion of SOX2-expressing cells occurred prior to HGSOC development, we analyzed the fallopian tubes of 48 women at high risk of developing ovarian cancer because they were BRCA1 or BRCA2 gene mutation carriers and therefore underwent prophylactic salpingo-oophorectomy." (PMID 27492892, 2016).
ovarian carcinoma (continued). "Mutations in BRCA1 may result in breast and/or ovarian cancer and pancreatic cancer." (PMID 27930734, 2016). "Thus, BRCA1 germline mutations appear to be an independent prognostic factor for ovarian cancer." (PMID 26753012, 2016). "However, further studies are required to determine which clinical features may better define a feasible link between breast/ovarian cancer and BRCA1/2 mutations." (PMID 25948282, 2015). "Since BRCA1/2 mutation status and familial susceptibility to ovarian cancer are familial conditions that concern close relatives, it is assumed that decision making may be influenced by personal experience and family perspectives or experience with cancer within the family." (PMID 26264902, 2015). "However, since our report on ovarian cancer, the spectrum of BRCA1 and BRCA2 mutations in this population has been further defined through comprehensive analyses of both genes, where 19 different pathogenic mutations in all have been found in French Canadian cancer families." (PMID 25884701, 2015). "This is the first comprehensive study of the BRCA1/2 mutation spectrum in Bulgaria and will assist the establishment of efficient protocols for genetic testing and individualized risk assessment for Bulgarian breast/ovarian cancer patients and healthy individuals at a high-risk." (PMID 26183948, 2015). "Such a dependency would also offer an explanation for the so-called “BRCA-paradox,” characterized by BRCA1/2 deficient embryonic tissues being anti-proliferative (thereby potentially causing embryo-lethality) but proliferative in malignant tumors, including breast and ovarian cancers." (PMID 25036526, 2014). "Additionally, it is conceivable that reversion mutations that restore the open reading frame of BRCA1, as has been documented for BRCA2, may also confer resistance to PARP inhibitor in breast and ovarian cancers expressing BRCA1 mutation." (PMID 25026298, 2014). "In conclusion, we provide evidence that the BRCA1 p.Ser36Tyr variant abrogates BRCA1 protein function and based on clinical, epidemiological, genetic and functional assay data we suggest that this variant is associated with a moderate risk of breast and ovarian cancer." (PMID 24695549, 2014). "However, BRCA1, an essential gene involved in DNA repair, has been reported to be evolving rapidly despite the fact that many protein-altering mutations within this gene convey a significantly elevated risk for breast and ovarian cancers." (PMID 25011685, 2014). "Moreover, the BRCA1/2 mutation status of an ovarian cancer patient can be an important aspect in regards to the decision of chemotherapy; BRCA1/2 carriers show increased sensitivity to platinum-based therapy, as well as to poly-ADP-ribose polymerase inhibitors." (PMID 23536787, 2013). "In current practice at the British Columbia Cancer Agency (BCCA), women with a strong family history of breast and ovarian cancer who meet specific eligibility criteria may be referred to the Hereditary Cancer Program to receive genetic counseling and testing for BRCA1/2 mutations." (PMID 23837641, 2013). "Therefore, our findings may represent a BRCA1-specific association with ovarian cancer risk, the first of its kind." (PMID 23544013, 2013). "Life-time risk for ovarian cancer is also high and may be up to 40% for BRCA1 mutation carriers." (PMID 24025454, 2013). "The analysis of another set of six genes, including MLH1 and BRCA1, with a previously established correlation between the methylation and expression status in borderline versus malignant tumors revealed that promoter methylation was associated with ovarian cancer risk and disease progression." (PMID 23344037, 2013). "In consequence, a patient known to be a carrier could receive PARP inhibitors early in treatment, making clinical genetic testing of RAD51D mutations in BRCA1/2-negative patients with one or more familial ovarian cancers in the pedigree potentially highly beneficial." (PMID 22415235, 2012).
ovarian carcinoma (continued). "While the exact OR values presented should be interpreted carefully due to a limited number of observations, the results indicate that SNP309 status may influence ovarian cancer risk with OR to a similar extent in BRCA1 mutation carriers as observed in sporadic ovarian cancer." (PMID 23039163, 2012). "Recent studies have revealed that several genetic polymorphisms may play important roles in the pathogenesis of ovarian cancer, and women who carried the gene mutation (BRCA1 mutation) had an increased risk (by up to 50%) of developing ovarian cancer in a lifetime." (PMID 23095717, 2012). "Therefore, the ovarian cancer of individual II:5 was most probably BRCA1-associated." (PMID 23164213, 2012). "The BRCA1 protein is classified as a tumor suppressor; in healthy cells it functions to maintain proper genomic repair and cell division, but inherited mutations in the BRCA1 gene encode altered forms of the protein that contribute to development of breast and ovarian cancer." (PMID 24278741, 2012). "Our choice of the four BRCA1 mutations: 5382insC (c.5266dupC), 300T>G (p.181T>G), 185delAG (c.68_69delAG), and 3819del5 (c.3700_3704del5) analysed in the present study reflects their high prevalence among Polish breast and/or ovarian cancer families and is based on the results of previous research." (PMID 22395474, 2012). "In women of Ashkenazi Jewish ascendance, up to 30% of breast and ovarian carcinomas may be attributable to mutations in these genes, where 3 founder mutations, c.68_69del (185delAG) and c.5266dup (5382insC) in BRCA1 and c.5946del (6174delT) in BRCA2, are commonly encountered." (PMID 22185575, 2011). "We have followed women at risk for breast and/or ovarian cancer for two decades, and report the prospectively observed age-related annual incidence rates to contract breast or ovarian cancer for women with deleterious BRCA1 or BRCA2 mutations based on 4830 observation years." (PMID 20180971, 2010). "We also found that phenotypic features such as high tumor grading and lack of expression of estrogen/progesterone receptors together with age at diagnosis and presence of ovarian cancer in the family may be predictive for the presence of BRCA1-2 germline mutations." (PMID 19619314, 2009). "Furthermore, recent findings suggest that BRCA1-associated ovarian cancers may require distinct strategy for the disease treatment." (PMID 19338682, 2009). "Univariate analysis indicated that presence of a BRCA1-2 mutation correlated significantly with earlier diagnosis age (P = 0.046), classification of the family as "high risk" (P = 0.002), recurrence in the family of ovarian cancer (P = 0.006), and development of a bilateral disease (P = 0.038)." (PMID 19619314, 2009). "Breast and ovarian cancers in women with BRCA1 mutations arise at an earlier age than sporadic cancers, so it was interesting to observe that, despite the difference in histologic phenotype, inactivation of Brca1 in mice resulted in tumors that developed more quickly." (PMID 20046869, 2009). "In addition to breast and ovarian cancer in women, and breast and prostate cancer in men, BRCA1 and BRCA2 carriers may be at higher risk for additional malignancies." (PMID 17213823, 2007). "However, the risk of ovarian cancer is also increased with the presence of the BRCA1 gene mutation." (PMID 16721370, 2006). "However, higher expression from Xp11 may be related to the earlier age of presentation of epithelial ovarian cancers in BRCA1 mutation carriers compared to tumors in BRCA2 mutation carriers and patients with sporadic ovarian cancer." (PMID 15383145, 2004). "In another study, ctDNA BRCA1 and BRCA2 reversal mutations were detected in 112 ovarian cancer patients treated with PARP inhibitors, with eight patients acquiring reversal mutations." (PMID 41602395, 2026). "Women with a BRCA1 or BRCA2 gene mutation are at increased risk of developing breast and ovarian cancer." (PMID 41025376, 2026).
ovarian carcinoma (continued). "Risk-reducing salpingo-oophorectomy (RRSO) is the most effective intervention for reducing ovarian cancer risk in women with hereditary breast and ovarian cancer syndrome (HBOC) associated with pathogenic BRCA1 and BRCA2 variants." (PMID 41717173, 2026). "Ovarian cancer with BRCA1/BRCA2 inactivation similarly shows heightened sensitivity to DNA-damaging therapy." (PMID 40841483, 2026). "Here we analyzed the 60KJPN dataset for BRCA1/BRCA2 variants and compared them with the previous version, 54KJPN, to ascertain the frequency of hereditary breast and ovarian cancers in the general Japanese population." (PMID 41565638, 2026). "Activation of HR is the critical event of treatment failure of PARPi in BRCA1/2 wild-type ovarian cancer (OC)." (PMID 41851090, 2026). "Pathogenic coding variants in BRCA1, BRCA2 and PALB2 confer hereditary breast/ovarian cancer risk, yet these regions comprise less than 10% of the genomic footprint of these genes, leaving most sequence unexplored." (PMID 41935071, 2026). "BRCA1 was predominantly detected in ovarian cancer, with 77.8% (7/9) of patients classified as on-tumor." (PMID 40926019, 2026). "Truncating variants in BRCA1, BRCA2, BRIP1 and RAD51D represent high‐risk variants for breast or ovarian cancer." (PMID 39440754, 2025). "For example, mutations in the BRCA1 and BRCA2 genes greatly elevate the risk of developing ovarian cancer." (PMID 41333220, 2025). "The concept of synthetic lethality, initially demonstrated in BRCA1/2-mutant breast and ovarian cancers, provides a new perspective on how defective homologous recombination (HR) renders tumor cells exceptionally vulnerable to PARP disruption." (PMID 40427518, 2025). "The current study is the largest single-institution study focusing on malignancies other than breast and ovarian cancer in women with a proven BRCA1/2 GPV." (PMID 40427184, 2025). "Following the promising results in breast and ovarian cancer, PARP inhibitors are being investigated in combination with ICI for PDAC with germline BRCA1/2 mutations." (PMID 39860372, 2025). "Being a carrier of mutations in the BRCA1 and BRCA 2 genes is one of the most well-known risk factors for ovarian cancer; 10–15% of all ovarian cancers have a genetic basis associated with these mutations." (PMID 40429755, 2025). "Mutations in BRCA1 and BRCA2 account for roughly 20–50% of hereditary breast-cancer cases and significantly increase women’s lifetime risk of both breast and ovarian carcinomas." (PMID 40843725, 2025). "Mutations in BRCA1 and BRCA2 genes are major contributors to ovarian cancer risk, as these genes play crucial roles in DNA repair through the homologous recombination pathway, ensuring cellular genetic stability." (PMID 40303993, 2025). "Women carrying BRCA1 mutations face a 39%-44% lifetime risk, while BRCA2 mutation carriers have an 11%-17% lifetime risk of developing ovarian cancer (American Cancer Society)." (PMID 40664665, 2025). "For instance, while BRCA1/2 alterations have strong evidence supporting PARP inhibition in ovarian cancer, the clinical significance of other DNA repair gene alterations remains less clear in many tumor types." (PMID 40209142, 2025). "Subsequently, mutations were discovered in BRCA1 and BRCA2, which are not only responsible for hereditary breast and ovarian cancer but also for prostate and pancreatic cancer syndromes." (PMID 41335382, 2025). "All patients diagnosed with ovarian cancer should undergo genetic counseling and testing for BRCA1/BRCA2 and other BRCA-related genes as recommended by guidelines." (PMID 40069521, 2025). "BRCA1 (breast cancer 1, early onset) is originally identified as a tumor suppressor in hereditary breast and ovarian cancer." (PMID 41347767, 2025).
ovarian carcinoma (continued). "In contrast, Tala + Deci also potentiated death in two independent BRCA1 mutant ovarian cancer cell lines (COV362, up to ~ 58% death; JHOS2 up to 35% death)." (PMID 39819384, 2025). "Mutations in pathogenic variants of BRCA1 and BRCA2 are reported to lead to lifetime risks of developing breast and ovarian cancer, as high as 84 and 45%, respectively." (PMID 40361383, 2025). "Women with a BRCA1/2 germline pathogenic variant (GPV) are at an increased risk of developing breast and ovarian cancer." (PMID 40427184, 2025). "In this cohort of 1347 women with a BRCA1/2 GPV, 82 malignancies other than breast and ovarian cancer were detected before age 60 in 37,068 person-years at risk." (PMID 40427184, 2025). "Early identification of mutations in BRCA1 and BRCA2 can have important implications for the diagnosis, treatment, and management of patients at high genetic risk of developing breast and ovarian cancer." (PMID 40071159, 2025). "BRCA1 has multiple roles, including initiating breast and ovarian cancer, in addition to its involvement in repairing DNA damage." (PMID 40286038, 2025). "We identified membrane, humbly, and extracellular matrix-associated genes specifically deregulated in BRCA1- and BRCA2-mutated breast and ovarian cancers through genomic mapping of public datasets." (PMID 40647506, 2025). "Specifically, there are two genes, BRCA1 and BRCA2, and mutations in these genes increase the risk of developing breast and ovarian cancer." (PMID 40070605, 2025). "Mutations in the BRCA1 and BRCA2 genes are the most significant genetic factors associated with an increased risk of developing ovarian cancer." (PMID 40664665, 2025). "Approximately 15% of non-mucinous epithelial ovarian cancer patients carry germline mutations in BRCA1 or BRCA2, and approximately 5–7% of ovarian cancer patients have somatic BRCA mutations." (PMID 40243501, 2025). "During the later 1990s, biotech startup Myriad had secured patents on the BRCA1 and BRCA2 genes, certain variants of which are associated with significantly elevated risk of breast and ovarian cancer." (PMID 39825701, 2025). "A pre-clinical study also showed that guadecitabine, a methyltransferase inhibitor, in combination with the PARPi talazoparib, inhibited breast and ovarian cancers harboring either wild-type- or mutant-BRCA1/2." (PMID 41020824, 2025). "Among these genomic alterations, BRCA1 and BRCA2—genes traditionally associated with breast and ovarian cancers—are emerging as key players in OSCC due to their roles in maintaining genomic stability and regulating DNA damage repair." (PMID 40224184, 2025). "Germline mutations in BRCA1 and BRCA2 predispose patients to around 40–70% of breast and ovarian cancers, making preventive strategies crucial for these patients." (PMID 40647506, 2025). "Mutations in BRCA1 and BRCA2 genes disrupt these repair mechanisms, predisposing individuals to an elevated risk of breast and ovarian cancers." (PMID 40599862, 2025). "The MEDIOLA ovarian study evaluated the association of the anti-PD-L1 durvalumab and PARPi olaparib in heavily pretreated patients with platinum-sensitive (n = 5) or resistant (n = 30) ovarian cancer, including six germline BRCA1/2 (gBRCA)-mutant patients." (PMID 41188872, 2025). "Important germline mutations related to breast and ovarian cancer such as BRCA1 and BRCA2 (BRCA1/2) have been identified, and other high- and moderate-risk genes have been found to be associated with increased risk for these cancers." (PMID 40710012, 2025). "The mutations in BRCA1 and BRCA2 genes are reported to increase the risk of ovarian cancer 12-fold and 5-fold, respectively." (PMID 40894326, 2025).